MUC1 (mucin 1, cell surface associated)
Diseases named in the same sentence as MUC1 in open-access papers (continued):
Sharing a sentence is not in itself a finding about the gene and the disease.
cancer (continued). "This was exemplified with the functionalizationof the Ce4+-ion-modified C-dots with the AS1411 aptamerand the MUC1 aptamer for the chemodynamic treatment of MDA-MB-231breast cancer cells and the in vivo inhibition of MDA-MB-231 tumorgrowth in mice." (PMID 36475576, 2022). "Over-expression of MUC1 reduces the adhesion of cancer cells with the outer matrix, so that the cancer cells easily detach from the original site and lead to the metastasis." (PMID 35197099, 2022). "These early findings collectively provided support for the potential importance of MUC1 as a cancer target." (PMID 35897789, 2022). "Another interesting phase I study used a humanized glycol-optimized monoclonal antibody against the MUC1 epitope (PankoMab-GEX) in different cancers." (PMID 36612133, 2022). "Our data validate that MUC1/ATAD3A/Pink1 axis-mediated mitophagy constitutes a novel mechanism for maintaining the malignancy of cancer cells, providing a novel therapeutic approach for MUC1-positive cancers." (PMID 36289190, 2022). "This hypoglycosylation exposes the variable number tandem repeat region (VNTR) which holds a number of cancer-specific MUC1 epitopes (MUC1-CE)." (PMID 36230945, 2022). "Despite this interest and the generation of anti-MUC1 TR immune responses, limited clinical benefit was observed in patients with cancer for advancing these vaccine approaches." (PMID 35897789, 2022). "MUC1, as well as CK-8 and CK-18, which are clinically utilized cancer markers, were also significantly higher in the cancerous-PEs, although their discrimination ability was generally lower." (PMID 35197508, 2022). "In ccRCC, MUC1 expression is induced by the HIF/hypoxia pathway and promotes the migration and invasion of cancer cells; however, the metabolic reprogramming associated with its overexpression is poorly understood." (PMID 36430448, 2022). "Here, we investigated the effect of MUC1 on mitophagy, dissected the potential underlying molecular mechanism, and uncovered the biological function of MUC1-related mitophagy in cancer." (PMID 36289190, 2022). "For example, binding of galectin-3 to the oncofetal galactose-β1,3N-acetyl-galactosamineα-Thr/Ser on the transmembrane mucin protein MUC1 in cancer cells induces MUC1 cell surface polarization." (PMID 36291660, 2022). "Taken together, PLA-PEG-Apt/DOX NPs can be used as targeted drug delivery system for efficient anticancer drug delivery to MUC1 positive cancer cells." (PMID 35304550, 2022). "This specificity likely originates from the fact that abnormal O-glycosylation occurs at MUC1 on cancer cells." (PMID 35887202, 2022). "Docetaxel increases surface expression of the carcinoembryonic antigen (CEA), calreticulin (CRT), mucin-1 (MUC-1) and Fas in cancer cells." (PMID 35874714, 2022). "In 2009, the National Cancer Institute had ranked MUC1 as the second most targetable antigen out of 75 to develop cancer vaccines." (PMID 35237602, 2022). "MUC1 helps TNBC cancer cells self-renew, probably through NF-κB (because NF-κB is linked to self-renew in BC cells)." (PMID 35248049, 2022). "CAR-T cell strategies targeting MUC1/MUC1-Tn have demonstrated encouraging results in preclinical studies using different in vivo cancer models." (PMID 35158915, 2022). "Third, cancerous MUC1 has a different structure from normal MUC1, which is overexpressed only on cancer cells." (PMID 35248049, 2022). "MUC-1 inhibits the binding of immune cells to their target and hinders the immunotherapy effectiveness in cancers with epithelial cells originally." (PMID 35000604, 2022). "MUC1-based DC vaccines can be prepared through the fusion of DCs with cancer cells that express MUC1, transfection using MUC1 RNA, and pulsing using the MUC1 TP peptide." (PMID 35883508, 2022).
cancer (continued). "So far different types of vaccines have been studied, e.g., cell-, DNA-, RNA- and peptide-based vaccines to deliver the MUC1 antigen, but the future of next generation cancer vaccines is mostly based on bioengineered nanostructures, such as VLPs." (PMID 35351156, 2022). "MUC1 has been also found aberrantly glycosylated in cancer compared to normal tissue, and some reported anti-MUC1 antibodies are actually against these aberrantly glycosylated variants." (PMID 35380164, 2022). "Overall, the identification of MUC1-dependent pathways is of potential importance in cancer research." (PMID 35154471, 2022). "NB also downregulated MUC1 which sensitized the stemness-high cancer cells to paclitaxel and inhibited spherogenesis." (PMID 36180880, 2022). "During the technique the MUC1 precise glycosylation on the cancer cell surface was pictured through a quantum dots label using the strategy of RMC magnification." (PMID 36259505, 2022). "Some PM proteins (such as the human epidermal growth factor receptors 2 (HER2), mucin 1 (MUC1), and epithelial cell adhesion molecules) have been identified as crucial cancer biomarkers." (PMID 36431072, 2022). "MUC1Apt is one of the most studied aptamers as it specifically recognizes the mucin 1 (MUC1) protein that is strongly upregulated in most cancer cell surfaces, which makes it a great target in cancer." (PMID 35785195, 2022). "Among such antigens, aberrantly glycosylated form of the membrane-bound mucin 1 (MUC1) expressed in multiple types of cancers is considered an attractive target for cancer immunotherapy." (PMID 35351156, 2022). "Glycosylated proteins, such as Mucin1 (MUC1), are being investigated as cancer-specific targets as they can have abberant glycosylation patterns and are overexpressed in some cancers." (PMID 35681750, 2022). "For mice immunization a formulation of purified chimeric MUC1-VLPs with TLR-independent adjuvant—squalene oil-in-water emulsion MF59 (AddaVax) was used to further boost the immune response to the potential cancer vaccine." (PMID 35351156, 2022). "Ongoing phase I clinical trial studies are examining Tn glycoform of MUC1-targeted CAR-T cells for the treatment in MUC-1 positive advanced cancers, including NSCLC (NCT04025216)." (PMID 35720364, 2022). "Recently, a cancer-specific glyco-epitope called the Muc1 protein (Tn-Muc1) was shown as a suitable target for CAR T cells against a variety of cancers." (PMID 35144648, 2022). "By inducing PDL1 expression through NF-κB and c-MYC activation in TNBC cells, MUC1 probably helps cancer cells escape from immune cells." (PMID 35248049, 2022). "Subsequent work demonstrated that MUC1 is aberrantly expressed in cancers originating from other diverse organs, including skin and immune cells." (PMID 36230728, 2022). "This is based on the fact that MUC1 undergoes aberrant glycosylation upon cancer progression, and anti-MUC1 antibodies differentiate changes in glycan structure." (PMID 35887202, 2022). "Other studies on the glycoprotein Mucin 1 (MUC1), known to be aberrantly glycosylated and highly expressed in various cancers, found that aberrant MUC1 expresses oligosaccharides such as sLex." (PMID 36552021, 2022). "Mucin1 (MUC1) is a transmembrane glycoprotein highly expressed both in malignant tumors and precancerous lesions." (PMID 35197099, 2022). "After confirming the binding ability of the constructed recombinant anti‐MUC1 nanobody to MUC1, efficacy and functionality of the nanobody against variety of cancer cell lines was evaluated with MTT and flow cytometry‐based apoptosis assays." (PMID 34694686, 2022). "The extracellular, transmembrane, and cytoplasmic domains of the MUC1 play varied roles in cancer progression." (PMID 36359337, 2022). "Bromelain can neutralize overexpression of the oncoglycoprotein MUC-1, which promotes the proliferation and enhancement of antiapoptotic properties of cancer cells along with invasion and chemical resistance in various human tumors." (PMID 36506883, 2022).
cancer (continued). "The evidence indicates that the transmembrane MUC1 subunit, which localizes to the cytoplasm and nucleus, is of importance for driving cancer progression and the cancer stem cell (CSC) state." (PMID 36230728, 2022). "MUC1 can be a marker for BC diagnosis because its expression is significantly higher in cancer tissue than in normal tissue." (PMID 35248049, 2022). "We further found that supernatant containing the MUC1.BiTE from HDTetra infected cells enabled AdVSTs to effectively kill MUC1+ cells in vitro, confirming the potential of this engager to re-target “irrelevant” effector cells against cancer cells." (PMID 35681750, 2022). "In normal cells, it provides protection against infection and inflammation, however, in cancer cells, MUC1 is aberrantly glycosylated and overexpressed and increases inflammation and aids oncogenesis." (PMID 35237602, 2022). "A long‐lasting response is a hallmark of immunotherapy, and ongoing responses after treatment discontinuation have been reported in mUC1, 8 and other cancers." (PMID 35864744, 2022). "β-catenin, E-cadherin, and MUC1 form a complex, decreasing cell junction, thus increasing the migration of cancer cells." (PMID 35248049, 2022). "The MUC1/SEC serves as MUC1/Y’s ligand, and it functions in initiating signaling events while changing cancer cell morphologies." (PMID 35883508, 2022). "Recently, MUC1 aptamers (Apt) have been developed to specifically target MUC1 protein for enhanced drug delivery in cancer treatment." (PMID 35304550, 2022). "MUC1 aptamer S2.2, is a 25-nucleotide small single stranded DNA with unique 3-dimensional structures which can selectively binds to MUC1-expressing cancer cells such as A-549 (human alveolar basal epithelial cells) with high affinity and specificity." (PMID 35304550, 2022). "MUC1 has been shown to be expressed up to tenfold higher on the surface of different human carcinomas than in healthy tissues." (PMID 35351156, 2022). "Among other mucins, involvement of MUC1 in malignant behaviors of carcinomas is widely acknowledged." (PMID 35410995, 2022). "It is also reported that the glycosylation pattern of MUC1 is different in normal and cancer cells, which is a positive point to be used for designing specific antibodies." (PMID 34679012, 2021). "Aptamers are selected to target cancer surface markers such as nucleolin and MUC1 or metastatic cell lines to detect various types of cancer or cancer metastasis." (PMID 33804856, 2021). "Among them, MUC1 and MUC16 were found to be associated with immune modulation and metastasis in cancer." (PMID 34327857, 2021). "In this review, we discussed MUC1 influence on the angiogenic-development of cancers under hypoxic conditions or in making interaction with pro-angiogenic factors such as VEGF, IGF, and related intracellular signaling cascades." (PMID 33836774, 2021). "Mucin 1 (MUC1) is a protein produced by human epithelial tissues, whose overexpression in blood serum can be a biomarker for cancer affecting various parts, such as the lungs, breast, pancreas, or bladder." (PMID 35056189, 2021). "The authors demonstrated flavone apigenin as the product inhibiting MUC1 gene and MUC1 cytoplasmic domain expression in cancer." (PMID 34681197, 2021). "Based on the available evidence, the elevated level of MUC1 is seem to be critical in cancer progression once an initiating oncogenic event has occurred." (PMID 33836774, 2021). "MUC1 has been reported to play a role in cancer development by suppression of cell death and promotion of metastasis." (PMID 34206951, 2021). "There have been substantial advances in MUC1-targeting cancer vaccines, i.e., subunit vaccines, DNA-based vaccines, viral vector-based vaccines, glycopeptide vaccines, and DC-based vaccines." (PMID 33692796, 2021). "The C-terminus of MUC1 has been more extensively studied, especially in the context of inflammation and cancer development, due to its location." (PMID 34207342, 2021).
cancer (continued). "MUC1 was identified almost 40 years ago, with cancer-specific aberrations in its expression pattern and glycosylation being recognized later." (PMID 34070311, 2021). "MUC1, a kind of pro-oncogenic mucin, is overexpressed in different cancer types and is an indicator of a poorer prognosis." (PMID 34639167, 2021). "In our research, we showed that 24 h incubation of AGS cancer cells with anti-MUC1 monoclonal antibody resulted in reduced expression of MUC1 gene as well as mucin expression in cell lysates and culture medium." (PMID 34206951, 2021). "Herein, we describe an in silico workflow to study a PPI involving Mucin 1 (MUC1) and Cbl-interacting protein of 85 kDa (CIN85) that has been associated with invasiveness and metastasis of cancer cells." (PMID 33672244, 2021). "Overexpressed cell antigens are expressed in normal cells, but significantly upregulated in some cancer cells, such as mucin 1 (MUC1) or epithelial membrane antigen, mesothelin and HER2." (PMID 34579759, 2021). "MUC1 is an epithelial cell surface protein that is overexpressed in over 90% of breast as well as other cancers." (PMID 34165702, 2021). "Bromelain also appears to impair cancer cell survival by blocking the ERK1/2 and pAkt/Akt, NFκB/MAPK pathway and attenuating Bcl-2 and mucin 1, cell surface associated (MUC1) oncoproteins." (PMID 34959865, 2021). "Several cancer vaccines, including a MUC1-based cancer vaccine, have successfully elicited an ADCC response." (PMID 33869008, 2021). "Our anti-MUC1-CAR4 T cells showed potent anti-cancer effect comparable to that of other studies in different cancer models using second- and third-generation anti-MUC1-CAR T cells, and also inverted cytokine receptor (IL-4R/IL-7) CAR T cells." (PMID 33737613, 2021). "When MUC1 acts in a pro-inflammatory manner, cancer cells use the vascular adhesion pathway of leukocytes in the inflammatory response to metastasis." (PMID 34207342, 2021). "MUC1 attenuates mitochondrial apoptotic factors such as cytochrome c or Bcl-xL (B-cell lymphoma-extra-large), protecting cancer cells from anti-cancer genotoxins such as cytarabine, gemcitabine, and cisplatin." (PMID 34681277, 2021). "Our results, in relation to NF-κB mRNA expression in AGS cancer cells, support the rationality of cisPt usage, as well as PtPz6 and anti-MUC1, as the factor was suppressed by such treatment." (PMID 34206951, 2021). "Other cancers also expressing MUC1 to a substantial degree include multiple myeloma, lymphoma and particular leukaemias." (PMID 34452200, 2021). "The p65/ZEB1 pathway that regulates the transcription of PD-L1, as well as TLR9, IFN-γ, MCP-1 (monocyte chemoattractant protein-1), and GM-CSF (granulocyte-macrophage colony-stimulating factor) in cancer cells, is activated by MUC1." (PMID 34681277, 2021). "First, MUC1 attenuates the genotoxic stress induced by DNA damage from DNA replication mechanisms or the actions of anti-cancer drugs." (PMID 34681277, 2021). "MUC1 can play either a pro- or anti-inflammatory role in different infection-induced cancers by acting as an immunomodulatory switch." (PMID 34207342, 2021). "In an experiment involving the coculture of CSCs and M2-TAMs, MUC1 and cancer stemness genes were shown to significantly increase." (PMID 34639167, 2021). "Together, these results are the next step in the use of these cancer-specific fully human anti-MUC1 antibodies for cancer immunotherapy, especially in the context of adoptive cell therapy." (PMID 34070311, 2021). "We chose one of the most promising agents (OM-86II) and we tested the combination of OM-86II together with the monoclonal anti-MUC1 antibody in the treatment of AGS cancer cells." (PMID 34770912, 2021). "Hyperactivation of these critical signaling pathways has been extensively observed in MUC1-positive cancer cells including pancreas, breast, lung, and colon." (PMID 33836774, 2021).
cancer (continued). "Cancer-related MUC1 proteins have shorter and less dense O-glycan side chains, resulting in exposure of the core domains of the protein on the cell surface." (PMID 34070311, 2021). "To further explore the therapeutic potential of anti-MUC1 antibodies for cancer immunotherapy, we generated fully humanized anti-MUC1 antibodies based on the 5E5 murine antibody." (PMID 34070311, 2021). "It preferentially recognizes the Tn- and STn-carrying GSTA region of MUC1, while PankoMab also recognizes the less cancer-specific T-carrying epitopes on the PDTR region." (PMID 34070311, 2021). "Based on these characteristics, researchers have designed different MUC1-targeting therapeutic approaches to treat cancer." (PMID 34207342, 2021). "Important leads have suggested that MUC1 is a promising target for the development of vaccines and a number of MUC1 peptide based cancer vaccines are currently in clinical trials." (PMID 33738611, 2021). "In the emerging field of tracking the targeted delivery of therapeutic agents to cancer cells, researchers have designed different types of vaccines aimed against the overexpression of MUC1, which can be effective in cancer prevention and treatment." (PMID 34207342, 2021). "Cancer cells evade stress-induced apoptosis through various mechanisms, and MUC1 has a protective role that contributes to this survival." (PMID 34681277, 2021). "Mucin 1 (MUC1) is an important target that is related to various cancer types, and the development of detection methods has always attracted people’s attention." (PMID 34770415, 2021). "This review summarizes recent findings on the composition of MUC1, its functions in different tissues (healthy and diseased), and its clinical applications, with a special focus on the impact of MUC1 on various aspects of cancer." (PMID 34207342, 2021). "We believe that our humanized anti-MUC1 antibody is a promising therapeutic candidate for clinical cancer treatment." (PMID 34070311, 2021). "For in vivo use, DNA aptamers (anti-MUC1, anti-nucleotide, anti-EGFRvIII, anti-cancer cell type-specific aptamer) and RNA aptamers (anti-PSMA aptamers) are used for cancer-specific detection using a variety of imaging." (PMID 34823601, 2021). "They found that MUC16 protein was frequently increased (65% of the patients) in the cancer patients, whereas MUC1 (30%) and MUC5AC (35%) proteins were less frequently elevated." (PMID 33672926, 2021). "Glycosylated MUC1 on cancer cells directly binds to selectin or siglec family proteins expressed on immune cells including macrophages and suppresses their functions." (PMID 34681277, 2021). "In melanoma, overexpression of MUC1 intervenes with integrin-mediated cell adhesion to the extracellular matrix and aggregates cancer cell invasiveness." (PMID 33836774, 2021). "Determination of the role of MUC1 with unique glycans during the process of cancer cell damage to the host is important because MUC1 has recently become an important target of advanced forms of diagnosis and therapy with antibodies and related molecules." (PMID 34641504, 2021). "The 5E5 antibody was previously shown to specifically recognize cancer-specific MUC1 epitopes (MUC1-Tn/STn) and elicits strong immune responses in mice." (PMID 34070311, 2021). "fabricated a series of aptamer-charged SERS probes (AS1411 and MUC1) for targeting cancer cells (MCF-7), and their results show the limit of detection (LOD) up to five cancer cells." (PMID 33718215, 2021). "The selective MUC1 aptamer-protein binding induced an unwinding of quenched sequence and fluorescence recovery to differentiate MUC1-positive cancer cells." (PMID 34620843, 2021). "Aberrant glycosylation of MUC1 results in random additions of sugar chains to MUC1′s five O-glycosylation sites on cancer cells." (PMID 34065557, 2021). "It is said that the interaction between Gal-3 and MUC1 increases cancer-cell–endothelial adhesion and, hence, promotes metastasis." (PMID 34681197, 2021).